CD63 (CD63 molecule)
Diseases named in the same sentence as CD63 in open-access papers (continued):
Sharing a sentence is not in itself a finding about the gene and the disease.
egg allergy (3 papers, 2020 to 2025). A food allergy that is an allergy or hypersensitivity to dietary substances from the yolk or whites of eggs, causing an overreaction of the immune system which may lead to severe physical symptoms. "The key elements in the diagnostics of hen's egg allergy include clinical history, skin tests, lab tests (sIgE/IgG4, BAT; CD63 and CD203c expression tests, component diagnosis, particularly in recurrent anaphylactic reactions) and/or elimination diets." (PMID 39800752, 2025). "sIgE levels and the percentage of basophils with the expression of CD63 were higher in patients with egg allergy than in those without egg allergy." (PMID 33291359, 2020).
gingivitis (3 papers, 2023 to 2026). A disorder involving inflammation of the gums; may affect surrounding and supporting structures of the teeth. "For example in that publication, oral and blood polymorphonuclear neutrophils with cluster of differentiation (CD) markers CD11b and CD63 were found to decrease over gingivitis induction but returned to baseline after restoration." (PMID 36966246, 2023). "This study also revealed a positive correlation between AZU and CD63 in patients with gingivitis, confirming that high levels of these biomarkers may reflect an increase in an innate immune response and activation of neutrophils in patients with periodontal diseases." (PMID 38813360, 2024).
glaucoma (3 papers, 2022 to 2024). Increased pressure in the eyeball due to obstruction of the outflow of aqueous humor. "In the regression analysis to determine the factors associated with glaucoma severity, the higher exosome particle count measured based on captured CD63 (CD63) was associated with a lower MD of the VF (p = 0.016)." (PMID 38920659, 2024). "Utilizing an optimized multiplexed magnetic bead-based flow cytometry assay, we observed a dominant CD63 APC fluorescence profile in two glaucoma (GLC) samples." (PMID 39519212, 2024). "The CD63 spot showed a particle count of 8319.1 ± 797.7 in PEX glaucoma patients and 4786.8 ± 1302.1 in controls (p = 1.88E−11)." (PMID 35896586, 2022).
Infertility (3 papers, 2016 to 2021). "We generated another line of Tg rats expressing human CD63-GFP under the Sox2 promoter, which expressed it in the kidney in addition to the brain; a large amount of urine output was observed, but no lethality or infertility was observed in either gender (unpublished)." (PMID 27539050, 2016).
influenza (3 papers, 2018 to 2023). An acute viral infection of the respiratory tract, occurring in isolated cases, in epidemics, or in pandemics; it is caused by serologically different strains of viruses (influenzaviruses) designated A, B, and C, has a 3-day incubation period, and usually lasts for 3 to 10 days. "We further studied the effects of age, SNF vs. Comm status, and influenza vaccination on proteins associated with platelet activation by assessing the basal expression of surface p‐selectin (CD62p, encoded by the SELP gene), CD40L, and CD63, prior to and following vaccination using flow cytometry." (PMID 36656789, 2023). "To assess if influenza and TLR7 can be located in the same platelet, we isolated platelets from an influenza-infected donor and stained for influenza, TLR7, and the lysosomal marker CD63." (PMID 30992428, 2019).
lymphoma (3 papers, 2021 to 2024). A malignant (clonal) proliferation of B- lymphocytes or T- lymphocytes which involves the lymph nodes, bone marrow and/or extranodal sites. "Compared with WT group, the expression levels of p-AKT, CD9, CD63 and PD-L1 significantly increased in WT + lymphoma group, suggesting that lymphoma cells can activate the AKT signaling pathway." (PMID 38261741, 2024). "The expression levels of p-AKT, CD9, CD63 and PD-L1 in KO + lymphoma group were significantly lower than those in WT + lymphoma group, demonstrating that Notch-1 is a key upstream molecule for the activation of AKT pathway in macrophages." (PMID 38261741, 2024). "The EVs markers; Tsg101 and CD63, and the lymphoma markers; CD45, CD79a, CD21, were detected in all EV samples." (PMID 36125986, 2022). "The EVs markers TSG 101, CD63 and lymphoma markers CD45, CD79a, CD21 were detected in patients with DLBCLs (L) and healthy dogs (C), CD20 was detected in one patient with DLBCL." (PMID 36125986, 2022). "Lymphoma cells enhanced the expression of p-PERK, p-IRE1α, ATF6, IL-6, IL-4, p-AKT, CD9, CD63 and PD-L1 in bone marrow-derived macrophages by mediating the Notch-1 signaling pathway." (PMID 38261741, 2024). "Moreover, the expression levels of p-AKT, CD9, CD63 and PD-L1 in WT + lymphoma cell + IXA4 group showed little changes compared with WT + lymphoma cell group, further proving that activation of the IRE1/XBP1s signaling pathway by IXA4 does not activate the downstream AKT signaling pathway." (PMID 38261741, 2024). "Our data showed these lymphoma vesicles did not strongly express CD63, LAMP-1, CD9, or TSG101." (PMID 33513976, 2021).
medulloblastoma (3 papers, 2012 to 2025). A malignant, invasive embryonal neoplasm arising from the cerebellum. "The pan-EV marker CD63 was expressed by parent medulloblastoma cells and a proportion of large EVs in viable cultures." (PMID 33218198, 2020). "Proteins commonly found in exosomes and microvesicles, namely, CD63, Alix, Flotillin-2 and TSG101, were present in EVs isolated from both non-treated and cisplatin-treated SHH and group 3 medulloblastoma cells and their corresponding whole cell extracts." (PMID 40495204, 2025).
non-small cell lung carcinoma (3 papers, 2023 to 2025). A group of at least three distinct histological types of lung cancer, including non-small cell squamous cell carcinoma, adenocarcinoma, and large cell carcinoma. "Similarly, Koh’s study identified CD63 as a prognostic marker for non-small-cell lung cancer (NSCLC), suggesting that low CD63 expression might serve as an adverse prognostic factor for NSCLC patients." (PMID 39194595, 2024).
oral squamous cell carcinoma (3 papers, 2019 to 2023). "In particular, we genetically engineered murine oral squamous cell carcinoma (OSCC) cell lines to express the vesicular membrane-associated protein CD63, fused with enhanced green fluorescence protein (CD63-eGFP) under the control of a CSC-specific promoter." (PMID 36735677, 2023). "Another pilot study with oral squamous cell carcinoma patients showed that the level of CD63+ exosomes decreased immediately after resection surgery, suggesting that the tumor was responsible for the high level of CD63+ exosomes in the circulation." (PMID 35757760, 2022). "Our pilot study wanted to analyse the relationships between the plasmatic exosome levels, positive for either CD63 or CAV-1, in patients with stage 4 oral squamous cell carcinoma without distant metastasis or local bone invasion, before and after surgical treatment." (PMID 30917536, 2019).
retinoblastoma (3 papers, 2023 to 2024). A malignant tumor that originates in the nuclear layer of the retina. "In studying patients with retinoblastoma, a primary pediatric ocular malignancy, we observed a significantly dominant subpopulation of CD63/81+ sEVs." (PMID 38892225, 2024). "In retinoblastoma eyes, the CD63/81+ sEV subpopulation was also hypothesized to be tumor-derived." (PMID 38892225, 2024).
septic shock (3 papers, 2021 to 2025). Shock caused by infection; frequently caused by gram negative bacteria, although some cases have been caused by other bacteria, viruses, fungi, and protozoa; characterized by fever, chills, tachycardia, tachypnea, and hypotension. "The group with higher exosomal CD63 levels was significantly associated with septic shock, requirement for mechanical ventilation or vasopressor support, and the severity of illness calculated using SAPS 3, APACHE II, and SOFA scores, 28-day, in-hospital, and 90-day mortalities." (PMID 34645935, 2021). "To evaluate the chemotactic, activation, and degranulation functions of neutrophils in patients with septic shock, we utilized flow cytometry to analyze the expression of CD10, CD121b, CD16, CD62L, and CD63 on neutrophils from HDs and septic shock patients." (PMID 40230851, 2025).
urticaria (3 papers, 2016 to 2025). A vascular reaction of the skin characterized by erythema and wheal formation due to localized increase of vascular permeability. "The CD63 expression on basophils appears as a reliable in vitro marker, useful in clinical practice in combination with autologous serum skin test to define chronic spontaneous urticaria patients with the highest urticaria activity that impairs a normal life." (PMID 27980778, 2016).
anaplastic astrocytoma (2 papers, 2018 to 2020). "Similar findings were obtained for the FASN+/CD63+ EV population in anaplastic astrocytoma patients (mean 2.9 × 105/mL AA vs 5.8 × 104/mL HD, P = 0.005) as well as for the FASN+/CD81+ EV population (mean 5.2 × 105/mL AA vs 2.3 × 105/mL HD, P = 0.03)." (PMID 32178271, 2020).
asthenozoospermia (2 papers, 2020 to 2021). "The exosomes isolated from normozoospermic men and asthenozoospermia patients were further identified by the presence of equal amounts of universal exosomal markers (CD63 and TSG101) based on immunoblotting." (PMID 34326815, 2021).
atopic dermatitis (2 papers, 2020 to 2023). "The expression of the tetraspanins such as CD9, CD37, CD53, CD63, CD81, and CD82 on FcεRIpos skin dendritic cells (DCs) from atopic dermatitis patients is significantly higher when compared to skin DCs of not allergic healthy individuals." (PMID 36672710, 2023).
chronic kidney disease (2 papers, 2018 to 2023). Impairment of the renal function secondary to chronic kidney damage persisting for three or more months. "Since CD63 is detectable in the urine of chronic kidney disease (CKD) model rats as well as in human urine, it might be considered a novel, non-invasive potential biomarker for FD." (PMID 37670295, 2023). "Additionally, in vivo identification of CD63 with calcification of vessels of chronic kidney disease (CKD) patients implicates that SMPD3 is a potential novel therapeutic target to inhibit EV genesis and thus vascular calcification." (PMID 29682509, 2018).
chronic obstructive pulmonary disease (2 papers, 2016 to 2022). A chronic and progressive lung disorder characterized by the loss of elasticity of the bronchial tree and the air sacs, destruction of the air sacs wall, thickening of the bronchial wall, and mucous accumulation in the bronchial tree. "In chronic obstructive pulmonary disease (COPD) or cystic fibrosis, changes in PMN phenotype after transepithelial migration, namely increased surface expression of CD66b and CD63, are due to an increase in the exocytosis of secondary and primary (NE-rich) granules." (PMID 35806233, 2022).
Cognitive impairment (2 papers, 2022 to 2024). Abnormal cognition is characterized by deficits in thinking, reasoning, or remembering. "Importantly, the NT-5/CD63 ratio in the serum EVs of patients with mild cognitive impairment was significantly lower than that in healthy volunteers, and the ratio was positively correlated with the MMSE score." (PMID 38321007, 2024). "Thus, NT-5/CD63 in serum EVs might be useful for the diagnosis of mild cognitive impairment, as in the case of SNAP25." (PMID 38321007, 2024).
coronary artery diseases (2 papers, 2011 to 2025). "Variables used in the stepwise logistic regression model included underlying age, gender, lipid profiles, coronary artery diseases, NIHSS score, pre-existing statin use, and CD62P and CD63 levels." (PMID 21740551, 2011). "Statistical analysis revealed that history of coronary artery diseases, NIHSS score on admission, pre-existing statin use, and platelet activation markers (CD62P and CD63) were significantly different between the good and poor outcome groups." (PMID 21740551, 2011).
cyst (2 papers, 2023 to 2025). A sac-like closed membranous structure that may be empty or contain fluid or amorphous material. "Examination of EV-associated markers suggested that there is an accumulation of CD63 in the apical aspect of the cyst epithelium." (PMID 40243914, 2025). "Thus, we applied anti-CD63-coated beads to isolate EVs from cell-free cyst fluids after a low-speed centrifugation, containing all EVs, and we analyzed the level of 377 miRNAs with low-density miRNA arrays." (PMID 37963969, 2023). "The subapical localization of CD63 in A-IC cells that lack primary cilia may be functionally relevant given the role that the primary cilia play in EV extrusion, especially because the A-IC cells that make up the cyst epithelium lack primary cilia." (PMID 40243914, 2025). "Comparison of CD63 and H+-ATPASE localization in the cyst epithelia of Tsc1KO mice revealed that CD63 levels were significantly elevated in the subapical region of H+-ATPASE-expressing cells; in comparison, the expression of CD63 was significantly lower in the normal epithelia of WT kidneys." (PMID 40243914, 2025). "We show that cyst fluid is a rich source of EVs that are positive and negative for the EV markers CD63 and CD81, respectively." (PMID 37963969, 2023). "Our results demonstrate the presence of intense subapical CD63 staining and its co-localization with apical H+-ATPASE in the cyst epithelia of Tsc1KO but not WT mice." (PMID 40243914, 2025).
dengue (2 papers, 2023). "In summary, our results suggest that PLT-EXOs isolated from dengue patients express CD63 and CD9 at significantly higher levels than healthy subjects and disease severity is associated with the increased secretion of PLT-EXOs in dengue patients." (PMID 38235130, 2023). "PLT-EXOs isolated from the dengue patients showed higher expression of CD63 and CD9 proteins than the healthy subjects." (PMID 38235130, 2023). "On immunoblotting, differential expression of CD63 and CD9 proteins was observed in the PLT-EXOs derived from dengue patients with different clinical presentations." (PMID 38235130, 2023). "On quantitation, fold change expression of CD63 and CD9 in PLT-EXOs was significantly higher in all the dengue patients (p=0.02, p=0.03), WS+ (p=0.001, p=0.029) and SDG (p=0.008, p=0.02) respectively than the healthy subjects." (PMID 38235130, 2023). "We observed that about two-thirds of the CD63+ SDV-EVs are also positive for a platelet marker CD41a, suggesting that platelets are the major contributors of EVs in the plasma of severe dengue patients." (PMID 37982662, 2023). "Of note, CD63 and CD9 expression levels were significantly higher on the PLT-EXOs isolated from dengue patients than the healthy subjects." (PMID 38235130, 2023). "Similar expression levels of CD63 and CD9 were seen when exosomes from primary and secondary dengue patients were compared." (PMID 38235130, 2023).
endometriosis (2 papers, 2018 to 2022). The growth of functional endometrial tissue in anatomic sites outside the uterine body. "Expression of both CD9 and CD63, exosome surface marker proteins, was observed on exosomes from both the endometriosis and control groups." (PMID 34542679, 2022).
fibrosarcoma (2 papers, 2021 to 2026). A malignant mesenchymal fibroblastic neoplasm affecting the soft tissue and bone. "To visualize exosome association with cytoskeletal structures, we stained for CD63 in HT1080 fibrosarcoma cells, which form numerous filopodia." (PMID 41532547, 2026).
Granuloma (2 papers, 2010 to 2022). A compact, organized collection of mature mononuclear phagocytes, which may be but is not necessarily accompanied by accessory features such as necrosis. "The presence of severe granulomas was associated with a profile of up-regulation of innate immunity-related genes such as complement factors C1q and C6, mannose binding protein, lysozyme C, C-type lectin receptor, CD209, Cathepsin D, CD63, LECT-2, CC chemokine and metallothionein." (PMID 20507624, 2010). "When compared to granuloma periphery or mucosa, CD68+ cells in the granulomata demonstrated increased gene expression in lysosome or macrophage-related genes such as CTSD, CD68, HEXB, ATP6V0A1, CTSK, LIPA, CD63." (PMID 36302964, 2022).
Hermansky-Pudlak syndrome (2 papers, 2011 to 2021). Hermansky-Pudlak syndrome (HSP) is a multi-system disorder characterized by oculocutaneous albinism, bleeding diathesis and, in some cases, neutropenia, pulmonary fibrosis, or granulomatous colitis. "Blood outgrowth endothelial cells from Hermansky-Pudlak syndrome patients carrying the AP3B1 mutation also lack CD63 in their WPB indicative of improper organelle maturation." (PMID 34977047, 2021). "In Hermansky-Pudlak syndrome, mutation of the β subunit of AP-3 results in mislocalisation of CD63, increased lysosome granule size and a failed release of lytic factors due to defective migration of intracellular granules." (PMID 21625559, 2011).
keratoconus (2 papers, 2023 to 2025). A degenerative, structural disorder of the eye, characterized by a cone-shaped protrusion of the cornea. "The results showed a significant decrease in CD63+/CD9+ and CD63+/CD81+/CD9+ expression in male EVs but not in female EVs with keratoconus." (PMID 40643480, 2025). "A recent evaluation of sEVs in tears from keratoconus eyes revealed that tear sEVs are neither mono-CD63+ predominant nor CD63/81+ predominant, reinforcing the intraocular nature of both subpopulations." (PMID 37410475, 2023).
kidney stones (2 papers, 2015 to 2022). "Similar comparisons between control males to males with kidney stones revealed that levels of phosphatidylserine and CD63 were higher in males with kidney stones." (PMID 35673574, 2022). "Comparison between control females to females with kidney stones showed that levels of CD63 positive uEVMPs were greater in females with kidney stones compared to control females." (PMID 35673574, 2022). "The total number of exosome (CD63) marker-positive EVs was greater in urine of women with kidney stones compared to control women." (PMID 25729563, 2015). "Sex-based comparisons showed that levels of CD63, MCP-1, and podocin plus galectin-1 positive uEVMPs were higher in females with kidney stones compared to males with kidney stones." (PMID 35673574, 2022).
liver cancer (2 papers, 2014 to 2022). An epithelial or non-epithelial malignant neoplasm that arises from the liver. "In the next experiments, we assessed the protein biomarker of sEV with FITC-conjugated mAbs specific to CD63 and CD9 derived from fresh liver cancer tissue, frozen liver cancer tissue and cultured liver cancer tissue sections." (PMID 34550537, 2022). "We next examined the relationship between CD151, CD63, and TM4SF5 in human liver cancer tissues." (PMID 25033048, 2014).
lysosomal disorders (2 papers, 2014 to 2023). "Lysosomal storage disease genes include GRN, GPNMB, GAA, and CHIT1 which, according to STRING analyses, interact with CD68, CD63, and TLR3, and are known to have lysosomal membrane function." (PMID 37422510, 2023).
mesothelioma (2 papers, 2010 to 2023). A usually malignant and aggressive neoplasm of the mesothelium which is often associated with exposure to asbestos. "Among the surface markers known to be expressed by mesothelioma cell lines, our cell cultures were strongly positive for CD46, CD47, CD56 and CD63, while showed a variable positivity for CD140b and CD141." (PMID 20175889, 2010). "Our cell cultures were strongly positive for CD46, CD47, CD56 and CD63 and were also strongly positive for some markers never described before in mesothelioma cell lines, including CD55, CD90 and CD99." (PMID 20175889, 2010).
metastatic melanoma (2 papers, 2013 to 2017). A melanoma that has spread from its primary site to another anatomic site. "Increased transcript level of Timp1 and CD63 was shown in different human metastatic melanoma cell lines compared to primary human melanocytes." (PMID 23522389, 2013).